ADH1B (alcohol dehydrogenase 1B (class I), beta polypeptide)
Diseases named in the same sentence as ADH1B in open-access papers (continued):
Sharing a sentence is not in itself a finding about the gene and the disease.
hemorrhagic stroke (2 papers, 2021 to 2022). A stroke caused by a bleed on the brain. "Future studies should examine hemorrhagic stroke risk and its association with ADH1B rs1229984 polymorphism and alcohol consumption in other ethnic groups, including East Asians and Caucasians." (PMID 34051793, 2021). "Our main finding suggested that ADH1B rs1229984 TC + CC genotype was a substantial risk factor (OR > 4.0) for hemorrhagic stroke in patients who drank more than 150 ml of alcohol per week." (PMID 34051793, 2021). "However, the risk of developing hemorrhagic stroke was significantly higher among ADH1B rs1229984 TC + CC individuals who drank alcohol (odds ratio (OR), 4.85; 95% confidence interval (CI) 1.92–12.21)." (PMID 34051793, 2021). "Our study suggests that the ADH1B rs1229984 TC + CC genotype and alcohol exposure of at least 150 ml/week may increase the risk of developing hemorrhagic stroke among Taiwanese adults." (PMID 34051793, 2021). "Stratification by alcohol exposure and ADH1B rs1229984 genotypes showed that the risk of developing hemorrhagic stroke remained significantly higher among alcohol drinkers with TC + CC genotype relative to those with the TT genotype (OR, 4.43, 95% CI 1.19–16.52)." (PMID 34051793, 2021). "Our study suggests that ADH1B rs1229984 TC + CC genotype, resulting in a slow ethanol conversion to acetaldehyde and alcohol exposure of at least 150 ml/week may increase hemorrhagic stroke risk among Taiwanese adults." (PMID 34051793, 2021). "Alcohol drinkers with the ADH1B TC + CC genotype may be predisposed to hemorrhagic stroke risk irrespective of the amount of alcohol intake." (PMID 34051793, 2021). "Our study revealed that the ADH1B rs1229984 TC + CC genotype, but not the slow acetaldehyde metabolizing ALDH2 rs671 variant increased the risk of hemorrhagic stroke with alcohol exposure." (PMID 34051793, 2021). "However, the study did not distinguish the specific effects of ADH1B and ALDH2 genotypes on hemorrhagic stroke in alcohol-drinking patients." (PMID 34051793, 2021).
Hepatic steatosis (2 papers, 2023 to 2024). Steatosis is a term used to denote lipid accumulation within hepatocytes. "However, studies on the association between hepatic steatosis, fibrosis and the influence of combining ADH1B and ALDH2 allele in patients with NAFLD remain scarce." (PMID 37240928, 2023). "In this study, the association between ADH1B/ALDH2 gene polymorphism and serum metabolic factors, body statures, and hepatic steatosis/fibrosis status was evaluated in patients with NAFLD." (PMID 37240928, 2023).
hyperuricaemia (2 papers, 2022 to 2024). "After stratifying by alcoholic beverage type, beer intake demonstrated the most significant interactions with ADH1B rs1229984 among men for association with serum urate level and hyperuricaemia, while wine intake demonstrated the most significant interactions among women." (PMID 38331848, 2024).
mental disorder (2 papers, 2023 to 2025). A disease that has its basis in the disruption of mental process. "We found that the ADH1B rs1229984 CC genotype increased the risk of alcohol‐induced mental disorders by 193% and of alcohol dependence syndrome by 295%." (PMID 35670037, 2023). "Thus, these ORs are far larger than for a typical GWAS finding in psychiatric disease – the risk effect being comparable to the effects of the functional ALDH2 and ADH1B variants on AUD and alcohol drinking." (PMID 41510264, 2025).
nicotine dependence (2 papers, 2014 to 2022). Physical and psychological dependence on nicotine. "We investigated six variants known to influence nicotine addiction or alcohol metabolism, including rs16969968 (CHRNA5), rs578776 (CHRNA3), rs1229984 (ADH1B), rs698 (ADH1C), rs1573496 (ADH7), and rs4767364 (ALDH2)." (PMID 24505444, 2014). "We found that the variants in alcohol dehydrogenase genes- rs1229984 (ADH1B), rs698 (ADH1C) and rs1573496 (ADH7) and the nicotine dependence gene variant rs16969968 were less common among Indians compared to previous studies in predominantly western populations." (PMID 24505444, 2014).
oral cancer (2 papers, 2023 to 2025). "Of particular note is the locus 4q23.3 containing the gene ADH1B, an alcohol metabolizing gene that has been associated with many alcohol-related conditions including oral cancer based on EA GWAS." (PMID 40321259, 2025). "For other GWAS-identified oral cancer susceptibility loci in European populations, we were able to replicate the loci on 5p15.33, the 4q23 ADH1B locus, and the LAMC3 locus on 9q34.12." (PMID 36769103, 2023). "We also confirmed the previously reported oral cancer susceptibility loci at the TERT-CLMPT1L locus on 5p15.33, thet 4q23 ADH1B locus, and the LAMC3 locus on 9q34.12 in Taiwanese populations." (PMID 36769103, 2023). "These GWAS identified at least nine genetic susceptibility regions for oral cancers, including 2p23.3 (GPN1), 4q21 (HEL308 and FAM175A), 4q23 (ADH1B, ADH1C, ADH7), 5p15.33 (CLPTM1L), 6p21 (HLA), 6p22.1 (ZNRD1-AS1), 9p21.3 (CDKN2A–CDKN2B), 9q34.12 (LAMC3), and 12q24 (ALDH2)." (PMID 36769103, 2023).
oral cavity cancer (2 papers, 2016 to 2023). A primary or metastatic malignant neoplasm involving the oral cavity. "ADH1B (rs122984) was associated better OS in HNSCC (p = 0.030) and OPSCC (p = 0.042) patients, but not in oral cavity cancer patients (p = 0.433)." (PMID 37706329, 2023).
oropharyngeal cancer (2 papers, 2020 to 2023). Carcinoma, predominantly squamous cell, arising from the epithelial cells of the oropharynx. "In oropharyngeal cancers, genome‐wide association analyses identify several loci, including rs1229984 in ADH1B, rs3828805 in HLA‐DQB1, rs4318431 nearby gene GALNT14, rs13211972 in MUC21, and rs34518860 in HLA‐DQA1, are correlated with patients' susceptibility and prognosis." (PMID 37706329, 2023). "When we removed the ADH1B variant found to be an outlier in the univariable MR analysis, the independent effects of both smoking and alcohol on risk of oral/oropharyngeal cancer persisted remained, although the magnitude of the effect was reduced for alcohol (IVW OR 2.1, 95% CI = 1.1, 3.8)." (PMID 33247085, 2020). "In a meta‐analysis of aerodigestive tract squamous cell carcinomas in patients of European ancestry based on a GWAS, ADH1B was found to play a significant role in oral and oropharyngeal cancer development." (PMID 37706329, 2023).
prostate carcinoma (2 papers, 2017 to 2022). A carcinoma that arises from epithelial cells of the prostate gland. "Combining the effects of the ADH1B SNP on alcohol intake with the upper confidence intervals from our results implies that a 17% reduction in alcohol consumption is unlikely to reduce prostate cancer risk by >3% and prostate cancer mortality by >5%." (PMID 27643404, 2017).
psoriasis (2 papers, 2019 to 2024). An autoimmune condition characterized by red, well-delineated plaques with silvery scales that are usually on the extensor surfaces and scalp. "We found that the frequency of the genetic variant rs1229984 (ADH1B) increased in the whole psoriasis group, while genetic variant rs1799971 (OPRM1) showed higher prevalence in the familial form of psoriasis patients." (PMID 31011876, 2019). "Analysis revealed association between C allele of the rs1229984 polymorphism (ADH1B gene) and psoriasis risk (ORadditive = 1.58, 95% CI 1.23–2.03, p < 0.001, ORrecessive = 1.58, 95% CI 1.22–2.04, p = 0.001)." (PMID 31011876, 2019).
steatosis (2 papers, 2015 to 2023). Increased lipid within the cytoplasm of cells. "The associations between metabolic factors, BMI, serum alanine transaminase (ALT), histological steatosis or fibrosis, and ADH1B/ALDH2 gene polymorphism were also analyzed." (PMID 37240928, 2023). "Another randomization study also determined that carriers of the ADH1B*2 allele had not only lower rates of alcohol consumption but also decreased scores of histologic steatosis, lobular inflammation, and NAFLD activity." (PMID 37240928, 2023). "Using biochemistry data, abdominal ultrasonography, fibrosis evaluation (Kpa), and steatosis evaluation (CAP), ADH1B gene SNP rs1229984 and ALDH2 gene SNP rs671 polymorphism were analyzed in sixty-six patients from 1 January 2022 to 31 December 2022." (PMID 37240928, 2023).
Abdominal obesity (1 paper, 2015). Excessive fat around the stomach and abdomen. "The highly significant correlations of ADH1B expression with WC provide evidence for a potentially greater role for this gene in central obesity which is highly correlated with IR." (PMID 25830378, 2015).
acute renal failure (1 paper, 2025). "For example, circulating ADH1B was a robust finding in the main analysis and was associated with acute renal failure, yet showed extensive cardiometabolic associations, arguing against renal specificity." (PMID 41282674, 2025).
alcoholic hepatitis (1 paper, 2024). Acute hepatitis resulting from ingestion of alcohol. "However, our analysis of the GSE28691 database showed that ADH1A and ADH1C were downregulated in liver tissues of patients with alcoholic hepatitis, while ADH1B and ADH5 showed no significant changes." (PMID 39044161, 2024).
alkaptonuria (1 paper, 2020). "ADH1B was found to be correlated with alcohol consumption-related cancer 36, while HGD was reported in alkaptonuria 38 and possesses at least 11 mutations and variants 39 in TCGA database." (PMID 32922552, 2020).
autoimmune hepatitis (1 paper, 2021). Hepatitis caused by autoantibodies. "ADH1B could not be detected in any of the serum samples collected from the two patients with autoimmune hepatitis before LT, although serum transaminases were elevated and the INR was >2.5." (PMID 34681731, 2021).
basal cell carcinoma (1 paper, 2015). A carcinoma involving the basal cells. "For example in MRC-5 fibroblasts, genes PGR and ADH1B belonging to pathways “Oocyte meiosis” and “Propanoate metabolism” were the only genes which were up-regulated and Wnt16 belonging to “Basal cell carcinoma” pathway was the only gene which was down-regulated with a log2 fold change >1." (PMID 26380578, 2015).
bipolar disorder-I (1 paper, 2022). "The authors found that having bipolar disorder-II and alcohol disorder may be related to ALDH2 and ADH1B, but having bipolar disorder-I and alcohol disorder may be related only to ALDH2." (PMID 35893041, 2022).
cerebral infarction (1 paper, 2012). An ischemic condition of the brain, producing a persistent focal neurological deficit in the area of distribution of the cerebral arteries. "Risk of MI did not change across ADH1B genotypes in a Danish population, whereas the ADH1B*1 allele coding for the slow isoenzyme was associated with a higher prevalence of cerebral infarction in Japanese men but not in women." (PMID 22363810, 2012).
colorectal tumors (1 paper, 2022). "Acetylation of Lys331 and Lys340 of ADH1B protein has been detected in high frequency for colorectal tumors that are paired with liver metastasis." (PMID 36923554, 2022).
developmental delays (1 paper, 2025). "We conducted a logistic regression analysis to explore the relationship between maternal drinking status during pregnancy and developmental delays in offspring with respect to maternal ADH1B (rs1229984) or ALDH2 (rs671) gene polymorphisms." (PMID 39537314, 2025). "This study aimed to elucidate the impact of maternal alcohol consumption during pregnancy on developmental delays in offspring, considering the polymorphisms of ADH1B and ALDH2, using a Japanese birth cohort study." (PMID 39537314, 2025). "Herein, we aimed to determine the involvement of ADH1B and ALDH2 gene polymorphisms in maternal alcohol consumption during pregnancy and the risk of developmental delay in offspring in a Japanese population." (PMID 39537314, 2025). "Effect of the combination of maternal drinking during pregnancy and ADH1B genotype on developmental delay in the offspring at 3 years of age." (PMID 39537314, 2025). "Our results did not detect any effect of ADH1B gene polymorphism on the association between maternal alcohol consumption during pregnancy and developmental delay in offspring at 3 years of age." (PMID 39537314, 2025). "Considering mothers with the ADH1B*1/*1 or *1/*2 genotype, analysis was impossible because there were no cases of developmental delay in the domains of communication and personal–social skills among children born to mothers who drank alcohol during pregnancy." (PMID 39537314, 2025).
endometriosis (1 paper, 2022). The growth of functional endometrial tissue in anatomic sites outside the uterine body. "In this study, we screened four characteristic genes of endometriosis (ACLY, PTGFR, ADH1B, and MYOM1) by using the full transcriptome sequencing data of clinical samples and public database resources." (PMID 35938015, 2022). "Hence, four genes were defined as characteristic genes for endometriosis by overlapping the genes derived from these two algorithms, including ACLY, PTGFR, ADH1B, and MYOM1." (PMID 35938015, 2022).
Graves disease (1 paper, 2023). Graves' disease is an autoimmune disorder that leads to overactivity of the thyroid gland (hyperthyroidism).It is caused by an abnormal immune system response that causes the thyroid gland to produce too much thyroid hormones. "ADH1B serves as an autotarget antigen for Graves’ disease, an autoimmune inflammatory disease." (PMID 37324256, 2023).
Hashimoto thyroiditis (1 paper, 2025). An autoimmune disorder caused by the production of autoantibodies against thyroid tissue. "considered ADH1B as one of the important genes linking Hashimoto’s thyroiditis (HT) and PTC, with potential diagnostic value." (PMID 40084144, 2025).
head and neck squamous cell carcinoma (1 paper, 2017). A squamous cell carcinoma that arises from any of the following anatomic sites: lip and oral cavity, nasal cavity, paranasal sinuses, pharynx, larynx, and salivary glands. "Genetic polymorphisms in ADH1B and/or ALDH2 can result in different enzymatic activities that have a major impact on the risk of ESCC as well as head and neck squamous cell carcinoma (HNSCC)." (PMID 28891965, 2017).
Hepatitis (1 paper, 2021). Inflammation of the liver. "With drug-induced ALI and HSV-induced hepatitis, circulating ADH1B was detected at very low levels (below LLOQ) at the earliest timepoints of the disease." (PMID 34681731, 2021).
keratoconus (1 paper, 2009). A degenerative, structural disorder of the eye, characterized by a cone-shaped protrusion of the cornea. "Microarray data analysis revealed up to a 212 fold reduction in the mRNA levels of alcohol dehydrogenase (class I) beta polypeptide (ADH1B) in the keratoconus fibroblasts (p=0.04)." (PMID 19365573, 2009). "Although other proteomics studies have shown that alcohol dehydrogenase is highly expressed by normal corneal fibroblasts, this current study has shown that ADH1B is the most downregulated gene in keratoconus fibroblasts at the transcript level." (PMID 19365573, 2009).
lipid metabolism disorder (1 paper, 2020). "The ADH1B variant is associated with lipid metabolism disorder, giving further link between alcohol intake and liver fat accumulation." (PMID 31998841, 2020).
lipodystrophy (1 paper, 2024). A congenital or acquired disorder characterized by abnormal loss or redistribution of the adipose tissue in the body. "The fact that human adipocyte differentiation appears to require ADH1B makes this an obvious candidate gene for lipodystrophy." (PMID 38838011, 2024). "In one such patient (with no pathogenic variant in the genes known to cause lipodystrophy), we found a homozygous missense variant which significantly impairs dimerization of the ADH1B monomers and alters the enzyme activity." (PMID 38838011, 2024).
liver cirrhosis (1 paper, 2025). "In such cases, the ADH1B*2 allele is believed to increase the risk of liver cirrhosis." (PMID 40943250, 2025). "In the group with high-titer anti-HCV antibodies and the ADH1B*2/*2 genotype, the adjusted odds ratio (AOR) for liver cirrhosis was 8.83 (95% confidence interval; 3.76–20.8)." (PMID 40943250, 2025).
liver dysfunction (1 paper, 2021). "The time-course for serum ADH1B concentrations was compared to the profile for standard biological indicators of liver dysfunction, including INR and ALT activity." (PMID 34681731, 2021).
lung squamous cell carcinoma (1 paper, 2023). "We also analyzed the relationship between ADH1B and survival in each cancer type and observed that ADH1B might increase the mortality risk in patients with lung squamous cell carcinoma (LUSC), stomach adenocarcinoma (STAD), and kidney renal papillary cell carcinoma (KIRP)." (PMID 37229243, 2023).
metastatic tumors (1 paper, 2025). "ADH1B activity levels in the serum of patients with BCa are significantly elevated, with higher activity potentially linked to metastatic tumors." (PMID 41001025, 2025).
non-Hodgkin lymphoma (1 paper, 2023). Distinct from Hodgkin lymphoma both morphologically and biologically, non-Hodgkin lymphoma (NHL) is characterized by the absence of Reed-Sternberg cells, can occur at any age, and usually presents as a localized or generalized lymphadenopathy associated with fever and weight loss. "ADH1B, CTH, and PLOD2 showed overexpression in the lymph node tissue of non-Hodgkin lymphoma patients compared to normal lymph node tissue." (PMID 36755971, 2023).
opioid use disorder (1 paper, 2022). A substance-related disorder that involves the recurring use of opioids despite negative consequences. "The authors suggested that the ADH1B*1/*1, ADH1B*1/*2, and ALDH2*1/*1 genotypes may interact and guard their carriers against opioid use disorder, and the protective effect may vary relative to DRD2 gene polymorphisms." (PMID 35743793, 2022).
pharyngeal squamous cell carcinoma (1 paper, 2016). A squamous cell carcinoma that arises from the pharynx. "We investigated the characteristics of ESCC, and the relationship between metachronous esophageal and/or pharyngeal squamous cell carcinoma (SCC) and the ADH1B & ALDH2 risk alleles." (PMID 27038040, 2016).
premature coronary artery disease (1 paper, 2012). "In a hospital-based case-control study from China, a somewhat lower prevalence of the slow-coding ADH1B*1/1 genotype was observed in patients with premature coronary artery disease (CAD) as compared to patients with late onset CAD (6.6% vs. 12.3%; p = 0.064)." (PMID 22363810, 2012).
sarcopenia (1 paper, 2024). Progressive decline in muscle mass due to aging which results in decreased functional capacity of muscles. "Then, ROC analysis was conducted to assess the diagnostic value of the target genes in sarcopenia, and the AUC values of CERS3, ADH1B, CYP26B1, and NNMT were greater than 0.7." (PMID 38838088, 2024).